CGAS (cyclic GMP-AMP synthase)
Diseases named in the same sentence as CGAS in open-access papers (continued):
Sharing a sentence is not in itself a finding about the gene and the disease.
tumor (continued). "In chemotherapy of ovarian cancer, cisplatin exposure boosted tumor immunogenicity via elevating calreticulin, MHC-I, antigen presentation, and T-cell infiltration through activating the cGAS/STING pathway." (PMID 35265630, 2021). "In chromosomal instability tumor cells, genomic DNA existed in cytoplasm activated cGAS-STING and downstream NF-κB signaling, promoting tumor cell invasion and metastasis." (PMID 33968056, 2021). "The abrogation of cytosolic DNA sensing via cGAS/STING and proinflammatory signaling diminishes PARPi cytotoxicity in mouse tumor models, indicative of uncompleted DNA repair products being the initial stimulus of this immune response." (PMID 33888558, 2021). "The cGAS-STING pathway is also often deregulated in cancer cells, supporting the view that it interferes with tumor growth." (PMID 34249949, 2021). "Apart from their functions in immunity, cGAS and STING also play major roles in nuclear functions and tumor development." (PMID 33708225, 2021). "The infiltration proportion of anti-tumor immune cells, including activated CD4+ T cell, activated CD8+ T cell and nature killer (NK) cell is higher in the cGAS-STING high cluster." (PMID 34625078, 2021). "For instance, therapies can activate the cGAS/STING pathway, thereby indirectly modulating T cell responses by modifying the relationship between the tumour and T cells (see also below)." (PMID 34885119, 2021). "In addition, released self-DNA, from dying tumor cells in the tumor microenvironment can be engulfed by intra-tumoral antigen-presenting cells (APCs), such as dendritic cells and macrophages and likely activates the cGAS-STING pathway, through mechanisms that are still under debate." (PMID 33981307, 2021). "Activating the cGAS-STING pathway to increase tumour inflammation thereby turning the tumours from “cold” to “hot” is one such strategy." (PMID 35006469, 2021). "By detecting micronuclei or cytoplasmic chromatin fragments induced by DNA damage, the cGAS/STING pathway can mediate the interplay between cytotoxic effects and immune stimulation, exerting a dichotomous effect on tumor tissue." (PMID 35046953, 2021). "On the other hand, the tumor cells need to evade this signaling pathway detection to survive in the harsh living environment; thus, IFN-I deletion and the cGAS/STING axis are observed to be disrupted in tumors." (PMID 35265630, 2021). "The cGAS/STING pathway, a cytosolic DNA receptor, has been regarded as an important mechanism to regulate inflammation-driven tumor progression." (PMID 35265630, 2021). "Chromosomal instability itself influences tumour immune infiltration, and also promotes inflammation by activating the cyclic GMP-AMP synthase-stimulator of interferon genes (cGAS-STING) pathway." (PMID 34968365, 2021). "We compared the ratio of these two categories of immune cells in different cGAS/STING clusters and observed that the cGAS/STING high cluster featured both higher anti-tumor immunity and pro-tumor immunity." (PMID 34625078, 2021). "STING can be activated by tumor DNA which produces type I IFN through the STING-IRF3 axis, or cytosolic DNA activates the cGAS-STING pathway and type I IFN production, independently of APC phagocytosis." (PMID 34858438, 2021). "Specifically, they showed that olaparib treatment induced cGAS–STING activation in breast cancer cells led to a paracrine activation of DCs and thus induction of a robust anti-tumor CD8+ adaptive immune response." (PMID 34884568, 2021). "Upregulation of TREX1 following lethal irradiation of tumor cells was recently reported to prevent cGAS-STING mediated IFN-I production in tumor cells and tumor infiltrating DCs." (PMID 33717156, 2021).
tumor (continued). "Increased DNA damage can trigger activation of the cGAS-STING pathway responsible for increased pro-inflammatory cytokine and chemokine expression that can recruit lymphoid and myeloid cells to control tumour growth." (PMID 34359633, 2021). "DNA-sensing receptor cyclic GMP–AMP synthase (cGAS) and its downstream signaling effector stimulator of interferon genes (STING) present a novel role in anti-tumor immunity." (PMID 34625078, 2021). "Increased PD-L1 expression following treatment with DDR inhibitors is mainly IRF3-dependent, and tumor-growth inhibition and immune-checkpoint blockade with DDR inhibitors is completely dependent on the cGAS–STING–IRF3 axis." (PMID 34488791, 2021). "In several tumor categories, methylation of TMEM173 (STING), TREX1, and C6orf150 (cGAS) was correlated with GMD expression." (PMID 33676569, 2021). "Recently, the combination of cGAS-STING agonists and immunotherapy achieved promising results in some tumor types." (PMID 34625078, 2021). "We evaluate BCG intratumoral treatment in a subcutaneous MB49 tumor model using different knockout (KO) mice (STING−/−, cGAS−/−, TLR2−/−, TLR3−/−, TLR4−/−, TLR7−/−, TLR9−/−, TLR3/7/9−/−, MyD88−/−, IL-1R−/−, Caspase1/11−/−, Gasdermin-D−/− and IFNAR−/−)." (PMID 34341449, 2021). "The cGAS/STING high cluster showed relatively higher ratio of immune cell infiltration, including cells with anti-tumor activity and immunosuppressive activity." (PMID 34625078, 2021). "In contrast to prior work demonstrating the importance of stromal cGAS–STING signaling in regulating the anti-tumor response to DNA-damaging therapies, this group demonstrated that the anti-tumor effects of olaparib required tumor cell cGAS–STING activation." (PMID 34884568, 2021). "Consistent with the essential role of cGAS-STING signaling in innate immune sensing and priming T cell-mediated anti-tumor immunity, STING is needed to mediate the anti-tumor effects of ICB therapy." (PMID 32774773, 2020). "Administration of cGAMP can reinforce the intensity of the cGAS-STING pathway, consolidating adaptive anti-tumor ability." (PMID 32887628, 2020). "Taken together, pieces of convincing evidence has revealed the dichotomous effects of the cGAS-STING pathway, although the complete mechanistic relevance of cGAS-STING signaling with respect to tumor development remains to be clarified." (PMID 32854711, 2020). "Increased tumour cell phagocytosis subsequently enhances antigen cross-presentation and activation of cyclic GMP-AMP synthase–stimulator of interferon genes (cGAS–STING) in APCs, resulting in more efficient T cell priming." (PMID 32198351, 2020). "Suppressing cGAS-STING signaling downregulates cytokine and senescence expression and inhibits apoptosis, protecting cancer cells from the host anti-tumor immunity." (PMID 32774773, 2020). "The results indicates that inhibition of NEAT1 results in the increase in cGAS, STING level, and upregulation of phosphorylation of TBK1 and IRF3 in both of cell lines and tumor samples." (PMID 32296457, 2020). "Thus, chronic cGAS-STING activation may promote tumor metastasis which needs to be overcome." (PMID 32571374, 2020). "cGAS-STING pathway agonists is a key activator, for the fact that hyperactivity of the pathway is significantly involved in tumor regression, prolonged survival time and enhanced immunity." (PMID 32887628, 2020). "cGAS/STING pathway is also related to tumor microenvironment remodeling and the production of anti-tumor cytokines such as indoleamine 2,3-dioxygenase (IDO), IL-10 and ISGs, together inhibiting tumor growth and improving the survival." (PMID 35006429, 2020). "The cGAS-cGAMP-STING-IRF3 pathway mediates the immune defense against infection, detects tumor-derived DNA and generates intrinsic antitumor immunity." (PMID 32596152, 2020). "Some studies have observed correlations between cGAS-STING pathway members, the tumor microenvironment, and cancer immunotherapy." (PMID 33006365, 2020).
tumor (continued). "cGAS-STING activation within the TME leads to an acute decrease in the proportion of tumor-infiltrating lymphocytes and an increase in tumor-infiltrating CD11b+ F4/80+ macrophages and CD11b+ F4/80- neutrophils." (PMID 32774773, 2020). "These consequences include a massive DNA rearrangement phenomenon called chromothripsis and activation of the cGAS-STING innate immune signaling pathway, which can be a double-edged sword with tumorigenesis and tumor prevention functions." (PMID 33230251, 2020). "The activation of the cGAS-STING pathway by both exported tumor dsDNA and cGAMP can partly be explained by the variable expression of cGAS and STING across different tumor cell types." (PMID 32774773, 2020). "The potent DNA damaging capacity of IR leads to activation of cGAS–STING and subsequent type I IFN production within tumor cells or DCs, facilitating optimal stimulation of CD8+ T cell-mediated tumor destruction." (PMID 33238631, 2020). "The cGAS-STING pathway is an important DNA-sensing machinery in innate immunity and viral defense, and critically involved in tumor development." (PMID 33006365, 2020). "Recent data implicate activation of the cGAS–STING pathway in DCs as critical for type I IFN production in the TME and the efficacy of radiotherapy in mouse tumor models." (PMID 33238631, 2020). "On the other hand, T‐MPs also activate the cGAS‐STING signaling, an important pathway for antitumor immunity, thus, conferring a potential role of T‐MPs in tumor immunotherapy and tumor vaccines." (PMID 32976623, 2020). "The mRNA expression of cGAS-STING pathway members, except for IFI16 and NLRC3, was significantly related with individual cancer stages and tumor grades in HCC." (PMID 33006365, 2020). "Chromosomal instability (CIN) in cancer cells has been reported to activate the cGAS–STING innate immunity pathway via micronuclei formation, thus affecting tumor immunity and tumor progression." (PMID 32284536, 2020). "By activating cGAS-STING signal in DCs, CD8α+ subtype DCs secret chemokines such as CCL5 and CXCL10 and cross-prime infiltrating anti-tumor CD8+ T cells." (PMID 32411126, 2020). "The cGAS-STING pathway mediates immune defense against infection of DNA-containing pathogens and detects tumor-derived DNA and generates intrinsic antitumor immunity." (PMID 32187211, 2020). "The ability of the cGAS-STING pathway to shape the inflammatory response via IFN-I signaling was recently identified in both spontaneous and radiation therapy-induced anti-tumor immunity." (PMID 32404939, 2020). "The phenomenon occurred due to the activation of the cGAS-STING pathway and the detection of tumor-derived DNA." (PMID 32887628, 2020). "Given the significant role the cGAS-STING pathway plays in cancer outcomes, there are currently a number of ongoing clinical trials assessing the anti-tumour potential of STING agonists as monotherapies or in combination with ICI." (PMID 33081170, 2020). "Analysis of TCGA database shed light on this tumor-intrinsic role, since loss-of-function mutations and epigenetic silencing occur in carcinomas across the cGAS-STING-TBK1-IRF3 axis, with a higher inactivation rate, the more advanced the tumor is." (PMID 33213060, 2020). "Importantly, cGAS was essential for the therapeutic effect of PD-L1 antibody as no therapeutic effect was observed in antibody-treated cGAS-deficient mice implanted with tumors: this is due to the need for activation of tumor-specific T cells to precede immune checkpoint inhibitor therapy." (PMID 32541866, 2020). "In the anti-tumor response, cGAS-STING activation was required for the recruitment of tumor specific CD8 + T cells and their infiltration into the tumor environment." (PMID 32404939, 2020). "This study indicates the careful use of cGAS-STING modulators in tumor therapy, including adjuvants in tumor immunotherapies in clinics." (PMID 33643304, 2020).
tumor (continued). "Overall, these studies support the synergistic actions of cGAS-STING activation and ICBs to attenuate immune tolerance in tumor cells and enhance the recruitment and priming of anti-tumor immune cells." (PMID 32774773, 2020). "On the other hand, lncRNA NEAT1 exerted its inhibitory effect on cGAS-STING pathway, mediating the immune escape of tumor cells to T cells." (PMID 32296457, 2020). "Chk1/2 inhibitors in combination with IR increased micronuclei formation (potentially increasing cGAS–STING activation) and type I IFNβ production in vitro and demonstrated improved immune-mediated tumor control in B16F10 melanoma models." (PMID 33238631, 2020). "On one hand, the cGAS-STING axis promotes the clearance of CIN tumors through recruitment of immune cells, thus suppressing tumor progression." (PMID 31658669, 2019). "Motivated by effective anti-tumor effect of DMXAA in mouse model, researchers have always been trying to find an appropriate human cGAS-STING agonist." (PMID 30935414, 2019). "In the co-culture test, NK and CTL resistant tumor cell usually had higher NLRX1 and NLRC3 level, which antagonized the expression of cGAS-STING-induced type I IFN." (PMID 30935414, 2019). "At this point the cGAS-STING signaling complex is formed which triggers type I interferon (IFN) production required for cross-priming of TAAs and the generation of tumor specific T cells." (PMID 30619273, 2018). "cGAS and STING have pivotal roles in cancer immunity and in the anti-tumor effects of immune checkpoint blockade." (PMID 30482235, 2018). "In summary, radiation seems to synergize with immunotherapy via several mechanisms, such as increasing the visibility of tumor antigens, activating the cGAS-STING pathway, and modulating the tumor microenvironment." (PMID 29556198, 2018). "Other than TLRs, cytoplasmic sensors such as cyclic GMP-AMP synthase (cGAS), RIG-I like receptors, MDA-5, DDX41, and DAI can recognize viral and tumor nucleic acids." (PMID 30186768, 2018). "DCs can also activate the cGAS–STING pathway after DCs phagocytose tumor cells and some of the tumor DNA escapes to the cytoplasm." (PMID 29050360, 2017). "We previously demonstrated that cGAMP, a product of cGAS and an agonist of STING, synergizes with IR to trigger a robust anti-tumor effect by enhancing the tumor-specific T cell response in the host." (PMID 29170400, 2017). "In particular, cGAS-STING signaling is important in sensing and responding to tumor cell-derived DNA." (PMID 28273161, 2017). "Severe side effects, including autoimmune and inflammatory response and direct tissue toxicity, limit the anti-tumor potential of Type I IFN therapy and cGAS/STING signaling modulation therapy." (PMID 29156566, 2017). "In this way, STING/cGAS in DCs is activated by DNA originating from dying cancer cells and critical for high levels of type-I IFN-1 generated during anti-tumor immune response and optimal cross-priming of T cells." (PMID 27854240, 2016). "Based on this, we hypothesize that promoter methylation silences cGAS-STING signaling, contributing to immune evasion and tumor progression." (PMID 40830678, 2026). "The activation of the cyclic GMP-AMP synthase(cGAS)- stimulator of interferon genes(STING) pathway initiates the expression of type I interferons (IFNs) and inflammatory cytokines, promoting the formation of a pro-inflammatory environment at the tumor site." (PMID 41751402, 2026). "Furthermore, the cGAS mRNA transcript showed a gradual increase and STING mRNA showed a decrease according to the tumor stage, tumor grade, metastasis status, and histology types." (PMID 41624260, 2026). "Furthermore, the peroxidase (POD)-mimetic and glutathione oxidase (GSHox)-mimetic activities of AMP@Zn/Mn-MOF can significantly potentiate tumor cell death and effectively induce robust immunogenic cell death (ICD), thereby amplifying the cGAS-STING pathway." (PMID 41603131, 2026).
tumor (continued). "In ferroptosis, cGAS–STING–induced IFN-β increases intracellular Fe2+ and lipid peroxidation, lowers glutathione, and upregulates TRIM22, thereby amplifying RSL3-induced ferroptosis in HCT116 and other tumor cells." (PMID 41601698, 2026). "Furthermore, released DOX and Mn2+ ions recruit tumor-killing immune cells by inducing the immunogenic cell death (ICD) of tumor cells and activating the cyclic GMP-AMP synthase-stimulator of interferon genes (cGAS-STING) pathway, respectively." (PMID 41852884, 2026). "Moreover, VPS34 shapes the tumor microenvironment (TME) through its influence on both immune and cancer cells by modulating autophagy, cGAS-STING (cyclic GMP-AMP synthase Stimulator of Interferon Genes), and STAT1 pathways." (PMID 41972724, 2026). "In cancers where cGAS or STING expression is silenced, reactivating this pathway may be a direct approach to restoring tumor immunogenicity or enhancing sensitivity to immune checkpoint blockade therapy." (PMID 40830678, 2026). "The activated cGAS-STING pathway secretes IFNs and chemokines, serving as a crucial bridge between innate and adaptive immunity, facilitating DC maturation, enhancing antigen presentation, and activating CD8+ T cells to recognize and eliminate tumor cells." (PMID 40830678, 2026). "Furthermore, we found that cGAS, STING, and galectin-9 expression levels were increased in LNP/pNC-treated tumor tissues compared with controls." (PMID 41424839, 2026). "The released mtDNA activates the cGAS-STING signaling axis, triggering a cascade of immune responses that effectively reverse the immunosuppressive TME, resulting in significant inhibition of tumor growth and metastasis." (PMID 41424843, 2026). "The cGAS-STING pathway is a cornerstone of innate antitumor immunity; however, its therapeutic potential is often limited by the inefficient cytosolic delivery of agonists and the immunosuppressive tumor microenvironment (TME)." (PMID 42201604, 2026). "Moreover, cGAS-STING signaling stimulates the expression of many chemokines which recruit immunosuppressive cells, such as MDSCs and Tregs, into the tumor microenvironment which subsequently promote metastasis." (PMID 41241888, 2025). "TRIM6-knockout murine models and subcutaneous tumors were subjected to flow cytometry, RNA sequencing, immunoblotting, and ubiquitination assays to characterize tumor-infiltrating lymphocytes (TILs), pathway activation, and TRIM6-mediated regulation of the cGAS-STING axis." (PMID 40817248, 2025). "84bp-TDNISD/56MESS not only effectively activates the cGAS–STING pathway as a delivery vehicle, but also releases 56MESS for effective chemotherapy and synergistically activates the cGAS–STING pathway, thereby preventing tumor metastasis and recurrence." (PMID 40486836, 2025). "Recent studies have also shown that Fusobacterium nucleatum-derived succinic acid may interfere with the cGAS-IFN-β pathway, a key player in CD8+ T-cell trafficking to the tumor microenvironment, thereby diminishing the antitumor response." (PMID 41002563, 2025). "The cGAS–STING pathway is multifaceted and influences tumor initiation and progression." (PMID 40470467, 2025). "Moreover, tumor cells employ repair mechanisms, including non‐homologous end joining (NHEJ) and homologous recombination (HR), to reduce cGAS‐STING pathway activation, resulting in inadequate type I interferon secretion." (PMID 40525676, 2025). "In recent years, advanced strategies have emerged that combine chemodynamic therapy (CDT) or photothermal therapy (PTT) with activation of the cGAS-STING pathway and blockade of the PD-1/PD-L1 axis, allowing for multi-targeted stimulation of anti-tumor immunity." (PMID 41007722, 2025). "In xenograft MM tumor models in immunodeficient mice, NK cells derived from human peripheral blood and expanded in vitro were combined with BiKE and cGAS-STING signaling agonists, demonstrating effective anti-tumor activity and inhibition of MM cell proliferation." (PMID 41417876, 2025).